MTX2 (metaxin 2)
Description:
Involved in transport of proteins into the mitochondrion.
Synonyms: MDPS; metaxin-2
Tractability: PROTAC: ubiquitination databases record sites on it; its protein half-life has been measured.
Gene: Protein-coding gene on chromosome 2 (176,269,395 to 176,338,025, forward strand). Ensembl gene ENSG00000128654.
Subcellular location: Mitochondrion outer membrane; Mitochondrion
Subcellular location (Human Protein Atlas): Mitochondria; Nucleoli
Pathways (Reactome):
Organelle biogenesis and maintenance: Cristae formation
Protein localization: Mitochondrial protein import
Gene Ontology:
Molecular function: protein binding
Biological process: mitochondrial transport; inner mitochondrial membrane organization; mitochondrial outer membrane translocase complex assembly; protein insertion into mitochondrial outer membrane
Cellular component: MIB complex; mitochondrion; SAM complex; mitochondrial outer membrane
Genetic constraint (gnomAD): Loss-of-function variants: 14 observed, 19.84 expected, observed/expected ratio (o/e) 0.71, 90% interval 0.47 to 1.1. The upper end of that interval is the gene's LOEUF score, 1.1, which puts it in group 4 of 6, group 1 being the genes least tolerant of losing a copy. Missense variants: 184 observed, 181.4 expected, observed/expected ratio (o/e) 1.01, 90% interval 0.9 to 1.15. Synonymous variants: 72 observed, 62.49 expected, observed/expected ratio (o/e) 1.15, 90% interval 0.95 to 1.4.
Gene-disease validity (ClinGen):
ClinGen rates the evidence that MTX2 causes each of these diseases.
mandibuloacral dysplasia progeroid syndrome (autosomal recessive): Definitive.
Homologues: Orthologues: chimpanzee MTX2 (100% identical), macaque MTX2 (99% identical), pig MTX2 (98% identical), rabbit MTX2 (98% identical), mouse Mtx2 (97% identical), dog MTX2 (94% identical), guinea pig MTX2 (89% identical), zebrafish mtx2 (81% identical), rat Mtx2 (78% identical), tropical clawed frog mtx2 (65% identical), Drosophila melanogaster CG8004 (42% identical), Caenorhabditis elegans mtx-2 (37% identical), and 1 more. Paralogues in human: MTX1 (30% identical), MTX3 (29% identical), FAXC (23% identical).
Diseases named in the same sentence as MTX2 in open-access papers:
MTX2 is named in the same sentence as 17 diseases in open-access papers, as found by Europe PMC text mining. Sharing a sentence is not in itself a finding about the gene and the disease. The quoted sentences say what the papers report.
mandibuloacral dysplasia (3 papers, 2020 to 2023). Mandibuloacral dysplasia (MAD) is a rare genetic bone disorder characterized by growth delay, postnatal development of craniofacial anomalies including mandibular hypoplasia, progressive acral osteolysis, mottled or patchy pigmentation, skin atrophy, and partial or generalized lipodystrophy. "Mandibuloacral dysplasia associated with MTX2 (MADaM) is a sever condition with symptoms including growth retardation and arises from homozygous null mutations in the human MTX2 gene." (PMID 37627305, 2023). "Here, we report a novel MAD progeroid syndrome (MADaM: Mandibuloacral dysplasia associated to MTX2) with clinical features resembling HGPS22,23, due to recessive mutations in MTX2 encoding Metaxin-2 (MTX2), an outer mitochondrial membrane (OMM) protein." (PMID 32917887, 2020).
mandibuloacral dysplasia progeroid syndrome (3 papers, 2021 to 2023). "A third type of mandibuloacral dysplasia progeroid syndrome (MDPS; OMIM #619127) due to biallelic variants in the MTX2 gene encoding metaxin-2 (MTX2) was recently described." (PMID 34680903, 2021).
autism (1 paper, 2012). Persistent deficits in social interaction and communication and interaction as well as a markedly restricted repertoire of activity and interest as well as repetitive patterns of behavior. "NEFL, SLC25A27 and MTX2 showed reduced expression in all the three brain regions of autism patients." (PMID 23116158, 2012). "MTX2, NEFL and SLC25A27 showed consistently reduced expression in the ACG, MC and THL of autism patients." (PMID 23116158, 2012). "The genes MTX2, NEFL and SLC25A27showed consistently reduced expression in all the three brain regions (ACG, MC and THL) of autism patients." (PMID 23116158, 2012). "In this study, we observed a downregulation of MTX2 in the ACG, MC and THL of autism patients; however, we did not observe an association of this gene with autism." (PMID 23116158, 2012). "Metaxin 2 (MTX2), neurofilament, light polypeptide (NEFL) and solute carrier family 25, member 27 (SLC25A27) showed consistently reduced expression in the ACG, MC and THL of autism patients." (PMID 23116158, 2012).
breast carcinoma (1 paper, 2022). "However, we found underexpression of EEF2 and GLRX2 proteins involved in ROS; MTX2 in MMO; USP30 in MIT; TSPO in MIT and PPM processes; BAX in FUS; and MTFR1L and MIEF1 in FIS compared to luminal A and basal-like breast cancer tumors." (PMID 35327574, 2022).
glioblastoma (1 paper, 2022). The most malignant astrocytic tumor (WHO grade IV). "In resting glioblastoma cells, Bak was identified as part of three complexes involving proteins from the mitochondrial importation/sorting machinery—namely, VDAC2/Mtx1/Mtx2/Bak, Mtx1/Mtx2/Bak, and Mcl-1/TOM70/Mtx2/Bak." (PMID 35204663, 2022).
infarction (1 paper, 2025). A localised pathological necrosis of tissue resulting from obstruction of the blood supply usually by a thrombus, an embolus, or vascular torsion. "Together, these findings demonstrate that activating PKM2, which is suppressed by MTX2 loss-of-function, can rescue myocardial apoptosis, infarction, and ventricular dysfunction during I/R." (PMID 40585998, 2025).
injury (1 paper, 2024). Damage inflicted on the body as the direct or indirect result of an external force, with or without disruption of structural continuity. "Here, we identified three novel mutations in MTX2, encoding a membrane protein in mitochondria, associated with multisystem manifestations including nephrotic proteinuria and kidney injury in two Chinese patients." (PMID 38250156, 2024).
renal failure (1 paper, 2024). "To well understand the development of renal failure in Pod-Mtx2-KO mice, we took a 40 weeks' follow-up." (PMID 38250156, 2024).
type 2 diabetes (1 paper, 2014). "Moreover, not only rare variant SNPs (in the Gpr155) but also common variants (in the Itga6, Zak, and Mtx2) could be candidate genes for type 2 diabetes caused by the gene-gene interaction." (PMID 24789282, 2014).
tumor (2 papers, 2021 to 2025). "These interactions indicate a complex network in which MTX2 modulates both metabolic pathways and immune responses, potentially affecting tumor progression and therapeutic efficacy." (PMID 40302794, 2025). "Increased expression of MTX2 promotes tumor growth by altering metabolic pathways and modulating the immune response, underscoring its potential as a new target for LUAD treatment." (PMID 40302794, 2025). "Functional analyses revealed that MTX2 regulates mitochondrial bioenergetics and facilitates tumor cell proliferation." (PMID 40302794, 2025). "MTX2's role in mitochondria and its involvement in the tumor immune system make it a potential therapeutic target." (PMID 40302794, 2025). "Single-cell RNA sequencing was utilized to further explore MTX2's role in immune infiltration and interactions within the tumor microenvironment." (PMID 40302794, 2025). "In summary, our results clarify the tumor suppressor roles of MTX2-6/miR-574-5p/SMAD4 axis in the progression of ESCC and provide emerging therapeutic targets for ESCC patients." (PMID 33869216, 2021). "In summary, our study clarified the tumor suppressor roles of MTX2-6/miR-574-5p/SMAD4 axis in ESCC, which provided prognostic markers and promising therapeutic targets for ESCC patients." (PMID 33869216, 2021). "Moreover, analysis using the TISIDB database revealed a correlation between MTX2 mRNA expression and tumor-infiltrating lymphocytes (TILs)." (PMID 40302794, 2025). "Notably, LUAD patient samples showed various MTX2 expression levels, highlighting its potential role in tumor progression." (PMID 40302794, 2025). "This study establishes MTX2 as a pivotal gene in various cancers, particularly in LUAD, by demonstrating its correlations with poor patient prognoses and tumor progression." (PMID 40302794, 2025).
cancer (1 paper, 2025). A tumor composed of atypical neoplastic, often pleomorphic cells that invade other tissues. "These interactions imply that MTX2 is pivotal for maintaining mitochondrial integrity and cellular energy metabolism, both of which are essential in cancer progression and prognosis." (PMID 40302794, 2025). "In this study, we investigated the significance of the MTX2 gene in LUAD, by exploring its biological roles, dysregulation in cancer, and potential as a diagnostic, prognostic, and therapeutic target." (PMID 40302794, 2025). "Our research revealed the differential expression of MTX2 across various cancer types, indicating consistent upregulation in a significant number of cancers compared to normal tissues." (PMID 40302794, 2025). "This suggests that MTX2 is integral to cellular stress responses and mitochondrial functions that are critical for cancer cell survival and proliferation in diverse malignancies." (PMID 40302794, 2025). "Based on TCGA and GTEx datasets, out of 24 cancer types studied, MTX2 was significantly upregulated in 17 types compared to normal tissues." (PMID 40302794, 2025). "Lastly, evaluating MTX2's specific roles and interactions in other cancer types could provide a more-comprehensive understanding of its oncogenic potential and improve prognostic accuracy, ultimately paving the way for improved patient outcomes." (PMID 40302794, 2025). "Moreover, MTX2 showed the highest expression levels in LUAD compared to other cancer types." (PMID 40302794, 2025). "KEGG and MetaCore pathway analyses further confirmed MTX2's involvement in OXPHOS and ubiquinone metabolism, which are crucial for sustaining cancer cell metabolism and survival." (PMID 40302794, 2025). "MTX2 has emerged as a promising biomarker and therapeutic target in LUAD, but it exhibits low cancer specificity, underscoring its involvement in broader oncogenic processes." (PMID 40302794, 2025).
cardiac diseases (1 paper, 2025). "Considering the important role of MTX2 in cardiac oxidative phosphorylation (OXPHOS) and glycolysis, these results provide proof of concept that targeting MTX2 might mitigate myocardial I/R injury and other cardiac diseases characterized by metabolic defects." (PMID 40585998, 2025).
MTX2 also shares sentences with these, for which no sentence is quoted: Brachycephaly (1 paper); glomerulopathy (1); Hypertension (1); laminopathy (1); lung adenocarcinoma (1).